SNHG27 (small nucleolar RNA host gene 27)
Gene: Long non-coding RNA gene on chromosome 4 (131,725,154 to 131,791,492, forward strand). Ensembl gene ENSG00000251676.
Diseases named in the same sentence as SNHG27 in open-access papers:
SNHG27 is named in the same sentence as 1 disease in open-access papers, as found by Europe PMC text mining. Sharing a sentence is not in itself a finding about the gene and the disease. The quoted sentences say what the papers report.
cancer (1 paper, 2024). A tumor composed of atypical neoplastic, often pleomorphic cells that invade other tissues. "Few of the lncRNAs in the SNHG family are known to be negative regulators of the inflammatory response, while SNHG18, SNHG27, and SNHG28 are reported to be associated with different forms of cancer." (PMID 38426128, 2024).